MUC1 (mucin 1, cell surface associated)
Diseases named in the same sentence as MUC1 in open-access papers (continued):
Sharing a sentence is not in itself a finding about the gene and the disease.
tubular adenocarcinoma (6 papers, 2013 to 2023). An infiltrating adenocarcinoma in which the malignant cells form tubular structures. "Frequent expression of MUC1 has been associated with the development of tubular adenocarcinoma, while MUC2 expression indicative of the presence of the intestinal metaplasia, which is frequently observed in IPNB lineage." (PMID 37721561, 2023). "The expression of MUC1 was significantly more frequent in invasive cases (87.5%) than in non-invasive IPNBs (50%), suggesting carcinogenesis leading to invasive tubular adenocarcinoma is associated with increasing aberrant expression of MUC1." (PMID 33317146, 2020). "The phenotype of PGC-/MUC1-/MUC2+ may be a predictive biomarker for diagnosing MA or SRCC or distinguishing from tubular adenocarcinoma accompanied by mucinous secretion or signet ring cell scattered distribution." (PMID 23937908, 2013). "It is thought that aberrant expression of MUC1 can lead to IPNB invasion, leading to tubular adenocarcinoma." (PMID 30875782, 2019). "Carcinogenesis via BilIN, predominantly associated with tubular adenocarcinoma, is characterized by a negative expression of MUC2 and an increase in the expression of MUC1, indicating the MUC1-positive pathway." (PMID 37721561, 2023). "The phenotype of PGC-/MUC1-/MUC2+ may be a predictive biomarker for diagnosing MA or SRCC, or distinguishing histological MA or SRCC from tubular adenocarcinoma accompanied by mucinous secretion or signet ring cell scattered distribution." (PMID 23937908, 2013).
breast adenocarcinoma (5 papers, 2015 to 2024). "After we had labeled MUC1-overexpressing MCF-7 cells (human breast adenocarcinoma cell line) with AptMUC1–Au NPs/GO, we used LDI-MS to monitor Au cluster ions ([Aun]+; n = 1–3), resulting in the detection of as few as 100 MCF-7 cells." (PMID 25973571, 2015). "Finally, MDA-MB-231 cells, a breast adenocarcinoma cell line negative for the expression of the MUC1-Tn antigen, were not very sensitive to GRNLY, and this cytotoxicity did not increase when using AR20.5GRNLY, confirming the usefulness of this cell line as a negative control for MUC1-Tn expression." (PMID 35740244, 2022).
chronic bronchitis (5 papers, 2016 to 2024). A type of chronic obstructive pulmonary disease characterized by chronic inflammation in the bronchial tree that results in edema, mucus production, obstruction, and reduced airflow to and from the lung alveoli. "Recently it has been shown that chronic bronchitis and smoking are associated with the presence of MUC1 and MUC4, as well as sub-epithelial cell fibrosis and airway wall thickening." (PMID 35205621, 2022). "The level of MUC1 expression correlated with lung function and was increased in individuals with chronic bronchitis, especially in females." (PMID 32948202, 2020). "We observed that smoking and a diagnosis of chronic bronchitis, but not airway obstruction, were associated both with increased MUC1 expression in cells suggesting basal cell phenotype, as well as the amount of soluble MUC1 protein in the airway lumen." (PMID 32948202, 2020). "Patients with chronic bronchitis had higher MUC1 expression." (PMID 32948202, 2020). "Wood smoke exposure resulted in increased expression of MUC1, MUC5AC, and MUC5B in the chronic bronchitis-like bronchial model." (PMID 38245732, 2024). "The level of MUC1 expression in large airways was higher in females with chronic bronchitis (p = 0.033) and these women had a higher level of soluble MUC1 (p = 0.021), but these phenomena were not evident in males (p = 0.21)." (PMID 32948202, 2020). "The expression of cell-bound and the concentration of soluble MUC1 were higher in subjects with chronic bronchitis as compared to non-bronchitic patients (p ≤ 0.0001 and p = 0.047, respectively)." (PMID 32948202, 2020). "In conclusion, we detected an association of MUC1 and MUC4 expression with smoking and with chronic bronchitis, but not with airway obstruction." (PMID 32948202, 2020). "Smoking history and the presence of chronic bronchitis, regardless of airway obstruction, affect both cellular and soluble MUC1 in human airways." (PMID 32948202, 2020). "Female subjects with chronic bronchitis had higher levels of MUC1 and MUC4 in comparison with the subjects without chronic bronchitis." (PMID 32948202, 2020).
cyst (5 papers, 2019 to 2025). A sac-like closed membranous structure that may be empty or contain fluid or amorphous material. "Histologic and cyst fluid biomarkers for high-risk IPMN, including KRAS, GNAS, and MUC1/MUC2/MUC4/MUC5A, will be used in future decision making about treatment." (PMID 33145018, 2020). "A cohort of 39 samples, comprising 33 cyst fluids and 6 blood plasma specimens, underwent thorough examination utilizing both the SiMoT array – targeting oncoproteins MUC1 and CD55, and oncogene KRAS – and the SIMOA SP‐X planar technology, focused exclusively on MUC1 and CD55." (PMID 38234100, 2024). "Within this system, oncoproteins MUC1 and CD55, along with the oncogene KRAS, are identified in either cyst fluid or blood plasma specimens from a cohort of 39 patients." (PMID 38234100, 2024).
ductal adenocarcinoma (5 papers, 2012 to 2019). "A need for revision of WHO classification of all ductal adenocarcinomas and subtypes of IPMN is suggested, also taking validated and recommended diagnostic use of MUC1 antibody, which recognizes fully glycosylated MUC1, into consideration." (PMID 30875782, 2019). "In contrast to MUC1, MUC5AC is not expressed by the normal pancreatic ducts but, similar to MUC1, in the majority of invasive ductal carcinomas and moreover already in the early PanIN lesions." (PMID 24783207, 2014). "Both CIN85 and the tumor form of MUC1 were expressed at significantly higher levels in invasive ductal carcinoma sections compared with normal epithelium." (PMID 24072600, 2013). "MUC5AC expression in differentiating ductal adenocarcinomas from benign conditions demonstrated better operating characteristics than either MUC1 or MUC6." (PMID 23197977, 2012). "Both membrane-bound (MUC1, MUC3, MUC4) and secreted mucins (MUC2, MUC5AC, MUC5B, MUC6) are upregulated in ductal adenocarcinoma of the breast." (PMID 30682816, 2019).
endometrioid carcinoma (5 papers, 2006 to 2025). "Apical MUC1 positivity was statistically more frequent in endometrioid carcinomas compared with carcinomas of non-endometrioid type." (PMID 16409624, 2006).
head and neck cancer (5 papers, 2017 to 2025). A primary or metastatic malignant neoplasm affecting the head and neck. "Some well-studied TAAs, epidermal growth factor receptor (EGFR, also known as ErbB-1 or HER1), carcinoembryonic antigen (CEA), mucin 1 (MUC1), human telomerase reverse transcriptase (hTERT), etc. are also expressed in head and neck cancers at high levels." (PMID 32942747, 2020). "The aberrant Muc1 expression occurs in many types of human cancers including colon, lung, pancreas, breast, ovarian, prostate, kidney, stomach and head and neck cancers." (PMID 29357376, 2018). "With regard to UICC stage, elevated MUC4 expression was referred to play a worse prognostic role in head and neck cancers (n = 1, RR = 0.56, 95% CI: 0.39-0.80, p = 0.002) than MUC1 (n = 9, RR = 0.87, 95% CI: 0.76-1.00, p = 0.052)." (PMID 29221212, 2017). "Muc1 have been attracted much attention as a cancer immunotherapy target as it is frequently overexpressed in many types of cancers, including colon, lung, pancreas, breast, ovarian, prostate, kidney, stomach and head and neck cancers." (PMID 29357376, 2018).
invasive carcinoma (5 papers, 2012 to 2020). A carcinoma that is not confined to the epithelium, and has spread to the surrounding stroma. "MUC1 is known to be associated with a higher risk of invasive carcinoma, as is MUC4." (PMID 33145018, 2020). "Similar to these observations, we observed strong expression of MUC1 towards luminal region of invasive carcinoma cases." (PMID 24671186, 2014). "Overexpression of MUC1 has been observed during the early stages of PC development, with a subsequent increase in expression in invasive carcinoma, both in humans and p48; KrasG12D; MUC1.Tg mouse model." (PMID 23102107, 2012). "However, the role of MUC1 expression in the transformation of premalignant lung lesions into invasive carcinoma is less well defined." (PMID 30479696, 2018). "The pathological findings revealed invasive carcinoma derived from IPNB, and immunohistochemistry revealed positive expression of MUC1, MUC5AC, and MUC6, but negative expression of CDX2 and MUC2." (PMID 33097064, 2020).
kidney failure (5 papers, 2021 to 2024). An acute or chronic condition that is characterized by the inability of the kidneys to adequately filter the blood. "Mutations in the MUC1 gene cause tubulointerstitial disease, which leads to kidney failure, and abnormal MUC1 signaling activation is linked to the development of CKD." (PMID 36766548, 2023). "Of particular interest is the strong correlation between mortality, renal failure, and MUC1 mRNA expression and between mechanical ventilation and MUC4 and MUC16 mRNA expression." (PMID 34448730, 2021). "Serum Mg2+ levels were associated with MUC1/TRIM46 (p = 2.9 × 10−7), SHROOM3 (p = 4.0 × 10−7), and SLC22A7 (p = 1.0 × 10−6) at nominal significance, which is in combination with the eQTL data suggesting that they are possible candidates for renal failure." (PMID 38279093, 2024). "Unlike MUC1, MUC1-fs encodes multiply repeated, Cys-containing unstructured neosequences whose cytotoxic entrapment, primarily in the cis-Golgi and coat protein I (COPI) compartments, ultimately leads to kidney failure." (PMID 39303030, 2024).
nasal polyps (5 papers, 2018 to 2025). "In vitro studies have demonstrated that stimulation with Staphylococcus aureus exotoxins induces IL-22 production, which in turn significantly enhances MUC1 mRNA expression in nasal polyp cells." (PMID 41295249, 2025). "Since the role of MUC1 in CRSwNP remains poorly understood, we decided to conduct an immunofluorescence study to evaluate MUC1 localization within nasal polyps’ samples and evaluate its potential correlation with disease severity." (PMID 41295249, 2025). "The epithelial cells of nasal polyps with high eosinophil count (>100/HPF) indicated a lower intensity of MUC1-FL with higher intensity of CCL4 than those with low eosinophils (<100/HPF)." (PMID 39791734, 2024). "Further analysis showed that the cytoplasmic tail (CT) part of MUC1 has anti-inflammatory effects on nasal polyp epithelial cells by inhibiting toll-like receptors (TLR).." (PMID 32812123, 2020). "Some studies investigated the pattern of expression of mucin in healthy nasal tissues and nasal polyps, which found that overexpressions of MUC1, MUC4, MUC5AC, and MUC5B are in nasal polyps than in healthy nasal tissues." (PMID 32812123, 2020). "The interaction of MUC1-CT forming a complex with GRα has been observed previously in beas2b bronchial epithelial cells and nasal polyp tissue confirming the results of this study." (PMID 30458870, 2018). "Based on this background, the current study aimed to investigate the expression of MUC1 in nasal polyps, its correlation with disease severity as assessed by Clinical Cytological Grading (CCG), and its interaction with other inflammatory cells, such as eosinophils and mast cells." (PMID 41295249, 2025). "Compared with normal nasal mucosa, the expression of MUC3 and MUC6 in nasal polyps is downregulated, the expression of MUC2 and muc8 in nasal polyps is upregulated, the expression of MUC5AC and MUC5B in CRS is upregulated, and the expression of MUC5AC in nasal polyps far exceeded MUC1 and MUC2." (PMID 32812123, 2020). "Therefore, CCL4 in mucin might be involved in the shedding of the MUC1 N-terminal domain; accordingly, the association between CCL4 and MUC1 expression in the nasal polyps of patients with CRSwNP was examined." (PMID 39791734, 2024). "Nasal polyp samples from patients with CRSwNP and BEAS-2B airway epithelial cells, coincubated with purified eosinophils, were stained with two MUC1 antibodies." (PMID 39791734, 2024). "Among the mucin family members, the expressions of MUC1, MUC2, MUC4, MUC5AC, and MUC5B have been detected in the human nasal polyp and middle ear epithelial cells." (PMID 32054887, 2020). "The immunofluorescence results revealed a negative correlation between the expression of full-length MUC1 and eosinophil count in nasal polyps." (PMID 39791734, 2024). "Studies on the expression of mucin in nasal polyps by using probes to be directed against unique sequence of mucin molecule (discontinuous repeat probes) show that expression level of MUC5AC is four times higher than MUC2 and is twelve times higher than MUC1." (PMID 32812123, 2020). "Recent data published by our group indicate that MUC1-CT is downregulated in patients with chronic rhinosinusitis with nasal polyps who did not respond to systemic corticosteroids." (PMID 30458870, 2018). "Furthermore, the expression of MUC1-FL was negatively correlated with the eosinophil count in nasal polyps (HPF), indicating that the N-terminal domain of MUC1 may be shed in eosinophilic airway inflammation." (PMID 39791734, 2024).
neuroblastoma (5 papers, 2016 to 2025). Neuroblastoma (NB) is the most common solid, extracranial childhood tumor. "No MUC1-ARF protein was detected in the neuroblastoma cell line SY5Y consistent with the undetectable expression of the MUC1 gene in these cells." (PMID 27768738, 2016).
prostate adenocarcinoma (5 papers, 2016 to 2025). "In NEPC tissues and compared to prostate adenocarcinoma, MUC1 was upregulated and negatively correlated with AR, which was suppressed." (PMID 40610411, 2025). "There are different expression levels of MUC1 –EMA epitopes that can be recognized in prostatic adenocarcinoma tissue compared with healthy cells." (PMID 35646176, 2022). "Among 333 prostate adenocarcinomas, 150 metastatic PCs, and 107 CRPCs, MUC1 gene is amplified in 1.8%, 6%, and 30% of the patient cohorts, respectively, demonstrating a unique amplification of the MUC1 gene in CRPCs." (PMID 27825118, 2016). "In PCa tissues, MUC1 protein was significantly overexpressed in advanced tumors with NED, compared to localized hormone-naïve prostate adenocarcinomas, while showing decreased AR immunoscore." (PMID 40610411, 2025).
acute kidney injury (4 papers, 2021 to 2024). Sudden and sustained deterioration of the kidney function characterized by decreased glomerular filtration rate, increased serum creatinine or oliguria. "In patients carrying MUC1 risk variants, recurrent episodes of acute kidney injury or chronic states of inflammation leading to HIF stabilization could potentially accelerate the development of CKD in the long run by increasing the abundance of toxic protein variants." (PMID 37316299, 2023). "To test for a potential role of hypoxia in regulating MUC1 expression in the distal tubule segments in cells suffering from acute kidney injury, we reanalyzed these single-cell RNA-seq data." (PMID 37316299, 2023). "Interestingly, in mouse models of ischemic acute kidney injury, MUC1 expression was also detected in proximal tubule cells." (PMID 37316299, 2023). "HIF stabilization and subsequent increases in MUC1 expression in renal tubular cells may occur because of reduced oxygen supply or a hypoxic microenvironment in the context of many renal diseases such as acute kidney injury or CKD and renal inflammation." (PMID 37316299, 2023).
ampullary adenocarcinoma (4 papers, 2011 to 2019). "The expression of MUC1 occurred more frequently than the other mucins studied, and it was associated with a higher degree of differentiation of ampullary adenocarcinoma." (PMID 22027009, 2011). "Positive IHC staining for CK7 and MUC1 was consistent with pancreatobiliary‐type ampullary adenocarcinoma." (PMID 31102323, 2019). "Expression of MUC1 was high (72%) in ampullary adenocarcinoma, while expressions of MUC2, MUC5AC, and MUC6 were lower." (PMID 22027009, 2011). "This study explored the relationships between diagnosis, identification, and survival of ampullary adenocarcinoma and the expressions of MUC1, MUC2, MUC5AC, and MUC6." (PMID 22027009, 2011). "For example, normal pancreatic tissue mainly expresses MUC1 and MUC6, while ampullary adenocarcinoma mainly expresses MUC1 and MUC5AC, along with MUC6 and MUC2." (PMID 22027009, 2011). "Three patients, 2 with metastatic ampullary adenocarcinoma and 1 with duodenal adenocarcinoma with positive IHC staining for CK7 or MUC1 who failed 2 lines of chemotherapy with oxaliplatin, irinotecan, and 5FU received nab‐paclitaxel and gemcitabine with or without cisplatin." (PMID 31102323, 2019). "In total, four out of eight cases showed poorly differentiated ampullary adenocarcinomas with prominent signet ring cells floating in the pools of mucous, two of these cases were positive for CK7, CK19 and MUC1, while only one was positive for CK7, CK19, MUC1 and CD10." (PMID 25202392, 2014). "The histomolecular (morphology plus IHC) pancreaticobiliary phenotype comprises ampullary adenocarcinomas that are of pancreaticobiliary histology with negative CDX2 and positive MUC1 expression by IHC." (PMID 27549176, 2016).
ampullary carcinoma (4 papers, 2010 to 2025). "Originally described in ampullary carcinoma, the INT versus PB dichotomy is defined by distinct H&E architecture and immunophenotype (e.g., CDX2/MUC1 patterns) and has been linked to clinical behavior." (PMID 41301018, 2025). "Although MUC1 has also been suggested to distinguish the pancreatobiliary subtypes of ampullary carcinomas, its use has not been independently validated and it mostly has been examined in conjunction with CK or CDX2." (PMID 38893239, 2024).
Arthritis (4 papers, 2018 to 2024). Inflammation of a joint. "In previous studies, M-M combined with BCG induced the Th1 dominant immune response, NK cell activity, MUC1-specific cytotoxic T lymphocyte (CTL) killing activity, and mouse MUC1 expression B16 cell (B16-MUC1) growth inhibition, but induced arthritis or local nodules in rats and cynomolgus monkeys." (PMID 29558459, 2018).
atherosclerosis (4 papers, 2013 to 2026). A disease characterized by the build-up of fatty material and calcium deposition in the arterial wall resulting in partial or complete occlusion of the arterial lumen. "We examined the association of MUC1 rs12411216 and rs4072037 genotypes with risk factors for atherosclerosis." (PMID 34638981, 2021). "Furthermore, MUC1 is known as a natural ligand for galactin-3, a suspected miscreant protein responsible for, among others, organ fibrosis, atherosclerosis, and HF." (PMID 34957244, 2021). "MUC1 (mucin 1) encodes a membrane protein involved in cell adhesion and signal transduction, not previously associated to smoking effects or atherosclerosis." (PMID 23372645, 2013).
autoimmune disease (4 papers, 2021 to 2023). A disorder resulting from loss of function or tissue destruction of an organ or multiple organs, arising from humoral or cellular immune responses of the individual to their own tissue constituents. "Further, MUC1 has been suggested as a checkpoint inhibitor on T cells, implicating MUC1, and possibly other membrane-bound mucins, in the development of autoimmune diseases." (PMID 35479093, 2022).